SSX1 (SSX family member 1)
Description:
Could act as a modulator of transcription. Plays a role in spermatogenesis.
Synonyms: CT5.1; SPGFX5; SSRC
Tractability: PROTAC: ubiquitination databases record sites on it.
Gene: Protein-coding gene on chromosome X (48,255,392 to 48,267,444, forward strand). Ensembl gene ENSG00000126752.
Subcellular location: Cytoplasm, cytoskeleton, flagellum axoneme
Subcellular location (Human Protein Atlas): Nucleoli; Nucleoplasm
Gene Ontology:
Molecular function: protein binding; transcription corepressor activity
Biological process: negative regulation of transcription by RNA polymerase II; spermatogenesis; regulation of DNA-templated transcription
Cellular component: nucleus; sperm flagellum
Homologues: Orthologues: chimpanzee SSX1 (94% identical), mouse Ssxb9 (34% identical), mouse Ssxb8 (34% identical), mouse Ssxb6 (33% identical), mouse Ssxb1 (32% identical), mouse Ssxb10 (32% identical), mouse Ssxb15 (32% identical), rat Ssx1 (32% identical), rat Ssx2 (32% identical), mouse Ssxb14 (32% identical), mouse Ssxb3 (32% identical), mouse Ssxb13 (31% identical), and 4 more. Paralogues in human: SSX4 (79% identical), SSX4B (79% identical), SSX7 (79% identical), SSX2 (78% identical), SSX2B (78% identical), SSX3 (78% identical), SSX5 (77% identical).
Diseases named in the same sentence as SSX1 in open-access papers:
SSX1 is named in the same sentence as 47 diseases in open-access papers, as found by Europe PMC text mining. Sharing a sentence is not in itself a finding about the gene and the disease. The quoted sentences say what the papers report.
synovial sarcoma (128 papers, 2001 to 2026). "The transcripts resulting from fusions of the SYT (at 18q11) gene with either SSX1 or SSX2 (both at Xp11) are diagnostic markers for synovial sarcomas." (PMID 34575830, 2021). "An additional example of translocated sarcoma is synovial sarcoma (SS), which is among the common histologies localized in the extremity and superficial trunk and is characterized by a translocation which causes the fusion of SSX1 or 2 or 4 with SS18." (PMID 34299136, 2021). "In this study, histology‐specific fusion genes were identified in nine cases, including SYT::SSX1 in synovial sarcoma, EWSR1::FLI1 in ES, and EWSR1::NR4A3 in EMC." (PMID 40755265, 2025). "Translocation t(X;18)(p11.2;q11.2) leading to the SSX1-SYT fusion has been implicated in development and invasiveness of synovial sarcoma." (PMID 39237765, 2024). "Certain subtypes are strongly associated with genetic fusions, such as Ewing’s sarcoma (EWSR1::FLI1), alveolar rhabdomyosarcoma (PAX3/7::FOXO1), and synovial sarcoma (SS18::SSX1/2/4)." (PMID 36980578, 2023). "We show that ICR-SS-1 grows readily in culture, retains the pathognomonic SS18::SSX1 fusion gene, and recapitulates the molecular features of human synovial sarcoma tumours as shown by proteomic profiling." (PMID 35954262, 2022). "On the other hand, synovial sarcoma is known to be well-characterized by a specific translocation resulting in gene fusion of SYT with either SSX1, SSX2, or SSX418." (PMID 31562358, 2019). "This patient had biopsy-proven metastatic synovial sarcoma with a known SS18/SSX1 fusion gene on molecular testing of the primary lesion." (PMID 30128716, 2018). "Although the SSX family of genes normally functions as suppressors, when SSX1 is fused to SYT1 in the SYT1-SSX1 gene in synovial sarcoma, the fused gene is capable of increasing the expression of both cyclin A and D1." (PMID 27649156, 2016). "The cytogenetically defined translocation t(X;18)(p11.2;q11.2) found in human synovial sarcoma results in the fusion of the SYT gene on chromosome 18 to SSX1, SSX2, or SSX4 on chromosome X at Xp11.2, leading to the formation of SYT-SSX fusion transcript." (PMID 27069481, 2016). "SSX genes were originally identified in synovial sarcomas with t(X;18) translocations, where SSX1 and SSX2 (and rarely SSX4) participate in oncogenic SYT-SSX fusions." (PMID 26380221, 2015). "SSX6 belongs to the SSX gene family, whereas SSX1, 2 and 4 have found to be involved in synovial sarcomas, SSX6 is expressed in melanoma cell lines." (PMID 25984793, 2015). "Major fusion partners of SS18 in synovial sarcoma are SSX1 and SSX2, and SSX4 has been reported in rare cases." (PMID 24130893, 2013). "This disease is characterized by a persistent t(X;18)(p11;q11) translocation event that juxtaposes the SYT (SYnovial sarcoma Translocated) gene on chromosome 18 with an SSX gene (either SSX1 or SSX2) on the X chromosome." (PMID 19337376, 2009). "Fusion of SYT to SSX1, SSX2 and SSX4 causes inappropriate transcription of SSX sequences in synovial sarcoma that is characteristic of this tumour group." (PMID 12592363, 2003). "Notably, the epigenetic regulator SS18 fuses with SSX1 in synovial sarcoma, forming the oncogenic SS18-SSX1 fusion." (PMID 40507965, 2025). "Nealy all synovial sarcomas (over 90%) have been identified with a chromosomal translocation between SYT and SSX genes, resulting in a fusion mutation of SYT to SSXs gene (including SSX1, SSX2, and SSX4)." (PMID 39748060, 2025). "The characteristic molecular hallmark of synovial sarcoma is the chromosomal translocation t(X;18)(p11;q11), which causes the fusion of the SS18 or Synaptotagmin (SYT) gene on chromosome 18 with one of the SSX genes (SSX1, SSX2, or SSX4) on the X chromosome." (PMID 40718269, 2025). "Nine SSX genes (SSX1–9) have been identified to date, but the contribution of each to synovial sarcoma remains unclear." (PMID 32322158, 2020).
synovial sarcoma (continued). "Synovial sarcoma is a well-established translocation-associated sarcoma and is defined by the presence of the t (X;18) (p11.2; q11.2) translocation, involving the SS18 (formerly SYT) gene on chromosome 18 and one of several synovial sarcoma X (SSX) genes on chromosome X (usually SSX1 or SSX2)." (PMID 30909651, 2019). "The last segment is on chromosome X [coordinates 48,000,001–48,500,000], with three known genes belonging to the family of highly homologous synovial sarcoma X (SSX) breakpoint proteins showed expression values within the higher 2.5th percentile: SSX1, SSX4 and SSX4B." (PMID 27611585, 2016). "Since SSX1 is predicted to be a target for miR-143 in in silico databases such as miRBase or TargetScan, it is speculated that its decreased expression in synovial sarcoma enables the production of the SS18-SSX1 oncoprotein." (PMID 25165708, 2014). "It is characterized by the typical translocation t(X;18)(p11;q11) that generates the fusion between the synovial sarcoma translocation, chromosome 18 (SS18 or SYT) gene on chromosome 18 and either synovial sarcoma, X breakpoint 1, 2 or 4 (SSX1, SSX2 or SSX4) genes on the X chromosome." (PMID 21609503, 2011). "Specific translocation has helped to classify synovial sarcomas as they typically show a t(X;18) translocation with fusion between SSX1 and SYT genes with a biphasic appearance in two-thirds of cases whilst the remainder show a fusion between SSX2 and SYT genes." (PMID 19335917, 2009). "In Synovial Sarcoma (SS), characterized by the fusion of the SS18 gene to either SSX1, SSX2, or SSX4, the expression of FOXM1 associates with poor prognosis and correlates with cell-cycle genes." (PMID 38946804, 2024). "Synovial sarcoma harbours a pathognomonic t (X; 18) translocation resulting in either SS18::SSX1, SS18::SSX2 or SS18::SSX4 fusion genes." (PMID 40666501, 2025). "Synovial sarcoma constitutes 5–10% of all soft tissue sarcomas and is characterized by its unique pathognomonic chromosomal translocations between SS18 and SSX1/2, and less commonly SSX4." (PMID 40563544, 2025). "Most cases of synovial sarcoma exhibit a fusion between the SS18 gene and either the SSX1 or the SSX2 gene, creating SS18-SSX1 or SS18-SSX2 gene rearrangements." (PMID 41149817, 2025). "Although synovial sarcoma is characterized by a simple karyotype and a translocation involving SS18 and SSX1, 2, or 4, omics studies are particularly crucial for patients who share the same karyotype but exhibit differing clinical prognoses." (PMID 39735532, 2024). "Fusion of the SYT gene on chromosome 18 with one of three homologous genes, SSX1, SSX2, and SSX4, on the X chromosome results in pathological tissue development of synovial sarcoma." (PMID 39583501, 2024). "It is worth noting that two SSX genes, namely, SSX1 and SSX2, are found to commonly be fused to SS18 in synovial sarcoma patients." (PMID 39045458, 2024). "For example, the COSMIC fusions SS18::SSX1 and SS18::SSX2, known drivers of synovial sarcoma, are in other clusters (C38 and C39), due in part to their higher 5′-FAR." (PMID 37323575, 2023). "Mutant SS18(3M)-SSX1 proved its incapability of colocalizing with BRG1, whereas SS18-SSX1-WT was able to recruit BRG1 into the phase-separated condensates in cells HEK293T and synovial sarcoma cell-line HS-SY-II or CME-1." (PMID 35585082, 2022). "For instance, beside the canonical fusion involving SS18 and SSX1 or SSX2, additional fusions involving SSX4 were called in 5/6 synovial sarcomas analyzed with the AMP-FPS panel." (PMID 32351889, 2020). "Synovial sarcoma is characterized by the translocation t(X;18)(p11;q11), which fuses SS18 (SYT) in chromosome 18 and SSX1, SSX2, or SSX4 (rarely) in chromosome X." (PMID 30487384, 2018). "Synovial sarcoma is defined by a characteristic translocation t(X;18)(p11.2;q11.2), which is observed in > 95% of cases and results in the fusion of SS18 to the SSX1, SSX2, or SSX4 genes." (PMID 29415665, 2018).
synovial sarcoma (continued). "A specific t(X;18)(p11.2;q11.2) translocation resulting in fusion of genes between SYT, on chromosome 18, and SSX1, SSX2, or rarely SSX4 on chromosome X is detectable in 90% of synovial sarcomas." (PMID 29531545, 2017). "The chromosomal translocation t(X;18)(p11.2;q11.2) fuses the SS18 (SYT) gene to the SSX gene (predominantly SSX1 or SSX2) and is regarded as a founding event in the oncogenic development of synovial sarcoma." (PMID 28191313, 2017). "The chromosomal translocation t(X;18)(p11.2;q11.2) is the main cytogenetic event in synovial sarcoma and results in the fusion of the BAF complex member SS18 with one of three highly homologous transcriptional repressor genes, SSX1, SSX2 or SSX4." (PMID 27120803, 2016). "Synovial sarcoma contains a characteristic translocation (X;18)(p11;q11), representing the fusion of SYT on chromosome 18 with either SSX1, SSX2, or rarely SSX4 on chromosome X." (PMID 25613038, 2015). "The 3′ region of the SSX-1, 2 and 4 genes are fused to nearly the entire SS18 gene in synovial sarcomas." (PMID 24787708, 2014). "The majority of cases of synovial sarcoma contain a t(X;18)(p11.2;q11.2) translocation that results in the fusion of the chromosome 18 gene SYT to three closely related genes SSX1, SSX2 and SSX4 on the X chromosome." (PMID 12592363, 2003). "To comprehensively interrogate the transcriptomic changes occurring in synovial sarcoma cells upon TAK-981 treatment, we treated HS-SY-II (harboring the SS18::SSX1 fusion) and SYO1 cells (harboring the SS18::SSX2 fusion) with DMSO or TAK-981 and performed bulk RNA sequencing." (PMID 40804185, 2025). "Importantly, nearly all synovial sarcomas bear the translocation t(X;18)(p11.2;q11.2), representing the fusion of SSX (including SSX1, SSX2, or SSX4 isoforms) with SYT." (PMID 39748060, 2025). "In synovial sarcoma samples, there is a chromosome translocation that results in the replacement of C-terminal 8 amino acids of wild type SS18 by 78 amino acids of SSX genes (SSX1, SSX2 or SSX4) to form onco-protein SS18-SSX." (PMID 38678233, 2024). "Using the HS-SY-II cell line, which has the SS18::SSX1 fusion gene as a positive control, we show that both ICR-SS-1 and its originating PDX tumour J000104314 harbour the SS18::SSX1 fusion gene, confirming the diagnosis of synovial sarcoma." (PMID 35954262, 2022). "Although some genetic features should have a very strong impact on the final diagnosis, such as the finding of an SS18::SSX1 fusion in a suspected synovial sarcoma, they are never sufficient." (PMID 35318454, 2022). "Synovial sarcoma (SS) is a rare soft tissue sarcoma that occurs in adolescents and young adults, with a pathognomonic t (X; 18) (p11.2; q11.2) chromosomal translocation, fusing the SS18 (formerly known as SYT) gene with the SSX1, SSX2, or SSX4 gene." (PMID 35126101, 2021). "More than 90% of synovial sarcomas are characterized by a specific chromosomal translocation, t(X:18)(p11.2: q11.2), that results in the fusion of the SYT gene on chromosome 18 to one of several SSX gene family members, (SSX1, SSX2 or SSX4), on chromosome X." (PMID 19936258, 2009). "Cytogenetics also plays a significant role in synovial sarcoma as both monophasic and biphasic types are characterized by reciprocal chromosomal translocations (x;18)(p11.2;q11.2), translocating the SYT of chromosome 18 to either of the two homologous genes SSX1 or SSX2 on Xp11." (PMID 40964824, 2025). "Synovial sarcoma (SS) is a subtype of sarcomas characterized by a translocation between SSX18 and SSX1, SSX2, or SSX4." (PMID 40249565, 2025). "Synovial sarcoma (SS) is a soft tissue sarcoma showing variable epithelial differentiation and is characterized by SS18::SSX1, SSX2, or SSX4 fusions." (PMID 36941503, 2023).
synovial sarcoma (continued). "SS is characterized by the translocation of ss18 gene on chromosome 18 and synovial sarcoma x (SSX) gene on chromosome X (usually SSX1 or SSX2), which is the driving factor of tumorigenesis and leads to the expression of SS18-SSX fusion protein." (PMID 36003502, 2022). "The precise etiology of synovial sarcoma remains unclear, however, a characteristic SYT-SSX fusion gene, which results from a t(X;18) translocation and represents a fusion of SYT (at 18q11) with SSX1, SSX2 or SSX4 (at Xp11), can be detected in more than 90% of synovial sarcomas." (PMID 33562681, 2021). "In synovial sarcoma, gene expression analysis revealed high levels of EGFR, SSX, ERBB2, IGFBP2, and IGF2 expression: this subtype of sarcoma is characterized by a translocation (X,18; p11,q11) which determines a fusion gene between SS18 and SSX1 (or SSX2) that exerts a key role in this neoplasm." (PMID 34207243, 2021). "Synovial sarcoma is a mesenchymal spindle cell tumor which displays variable epithelial differentiation and has a specific chromosomal translocation t(X; 18) (p11; q11), which results from the fusion of the SYT gene on chromosome 18 to exon 5 of either SSX1 or SSX2 genes on chromosome X." (PMID 29751751, 2018). "DNA sequencing showed that the fusion sites of all SS18-SSX1 and the four classical SS18-SSX2 tumors were involved in exon 10 of the SS18 gene (codon 410) and exon 6 of the SSX1 or SSX2 genes (codon 111), which is typical of the ordinary fusion site of synovial sarcoma." (PMID 27401493, 2016). "It is interesting to note that the SSX1/2 part of the fusion proteins with SS18 derived from the t(X;18) translocation in synovial sarcoma does not contain the aKRAB of SSX." (PMID 35162997, 2022).
sarcoma (15 papers, 2010 to 2025). A usually aggressive malignant neoplasm of the soft tissue or bone. "Interestingly, our most up-regulated gene, SSX1, encodes a protein that also is involved in chromatin modulation, and is already involved in sarcoma oncogenesis." (PMID 20576167, 2010).
breast carcinoma (5 papers, 2001 to 2023). "Additionally, antibodies specific for SSX1, 2, 3, and 4 have been found in the sera of cancer patients with melanoma, colon cancer, and/or breast cancer." (PMID 20981248, 2010). "These analyses identified more frequent CT expression in estrogen and progesterone receptor negative breast cancer, including NY-ESO-1, LAGE-1, MAGEA, PAGE4 and SSX1." (PMID 21437249, 2011).
melanoma (5 papers, 2010 to 2022). A malignant, usually aggressive tumor composed of atypical, neoplastic melanocytes. "To get an insight into the function of SSX in tumor cells, we silenced SSX in the melanoma cell line DFW that expresses SSX1 to SSX5 using plasmids for both stable and doxycycline conditional expression of shRNA molecules targeting SSX1–9 transcripts as described in material and methods." (PMID 24787708, 2014). "In accordance with previous small cohort studies, the highest occurrence and expression levels were observed for SSX1 and SSX2, with 89% of primary melanomas and 88% of metastases having expression of either SSX1, SSX2 or both." (PMID 36276095, 2022). "Meanwhile, profiles of expression of HAGE, PASD1, SEMG1, SLLP1, SPANXA1, SSX1 weren’t significantly different in STBS and melanoma cell cultures at the complex assessment." (PMID 32042403, 2020). "Resembling the clinical melanoma samples, all SSX genes could be detected in FM6, FM79 and CBK14797 before knockdown, but the expression was dominated by SSX1 and SSX2." (PMID 36276095, 2022). "Interestingly SSX2 was detected in almost all melanoma tissues and derived cell lines (95%) compared to SSX4 (57%), SSX1 (38%), SSX5 (33%) and SSX3 (19%) expression." (PMID 24787708, 2014).
colon cancer (3 papers, 2020 to 2023). "The expression of SSX1 gene is related to the poor prognosis of patients with colon cancer (Hilal, Novikov, Novikov, & Karaulov, 2017)." (PMID 31273792, 2020).
multiple myeloma (3 papers, 2010 to 2023). "SSX1, SSX2, and SSX4 are expressed in Hodgkin's lymphoma and head and neck cancer, while SSX1, SSX2, SSX4, and SSX5 are expressed in multiple myeloma." (PMID 27276714, 2016). "Additionally, SSX1 has been observed to be prognostic for both OS and progression-free survival (PFS) in patients affected by relapsed myeloma." (PMID 36649303, 2023).
astrocytomas (2 papers, 2006 to 2010). "SSX expression has also been evaluated by RT-PCR in brain tumors in which SSX1 was only expressed in astrocytomas, while SSX2 was expressed in astrocytomas and oligoastrocytomas, and SSX4 was expressed in both of these as well as oligodendrogliomas." (PMID 20981248, 2010).
osteosarcoma (2 papers, 2014 to 2020). A usually aggressive malignant bone-forming mesenchymal neoplasm, predominantly affecting adolescents and young adults. "To investigate the validity of this observation we also performed siRNA knockdown of SSX expression in two additional osteosarcoma cell lines, U2-OS and Saos-2, using RNAi molecules targeting SSX1–9, or specific for SSX1 and SSX2." (PMID 24787708, 2014). "Osteosarcoma was characterized by the presence of GAGE (40% 2/5), MAGEA1 (60% 3/5), PRAME (40% 2/5), NY-ESO1 (40% 2/5), PASD1 (60% 3/5), SLLP1 (60% 3/5), SSX1 (80% 4/5)." (PMID 32042403, 2020).
adenoma (1 paper, 2024). A neoplasm arising from the epithelium. "In the LNM-positive group compared to the control adenoma, there were significant increases in gene expression for CCL15, SSX1, and KRT5 genes, alongside significant decreases in HLA-E, ITPK1, ANXA1, and TXNIP genes across the head, proximal stalk, and distal stalk regions." (PMID 38256174, 2024).
carcinosarcoma (1 paper, 2015). A malignant tumor composed of a mixture of carcinomatous and sarcomatous elements. "More than 90 % of SS present this translocation, which gives rise to a fusion gene, SS18 (SYT)-SSX (SSX1 or SSX2, or both), whereas MPNST and carcinosarcoma lack SS18-SSX fusions." (PMID 26112006, 2015).
colon adenocarcinoma (1 paper, 2023). "The study examined the expression levels of the SSX1, SSX2, and SSX3 genes in NC and colon adenocarcinoma (COAD) tissue samples using RNA sequencing data from the TCGA repository (accessed on 20 February 2023)." (PMID 37241221, 2023).
colorectal cancer (1 paper, 2023). A primary or metastatic malignant neoplasm that affects the colon or rectum. "Our RNA-Seq analysis also found that 5’-Aza-CdR exposure resulted in overexpression of multiple CT antigens in gastric cancer and colorectal cancer, including SSX1, TKTL1, SPANXB1, PNMA5, PNMA6E, GAGE12J, and PRSS56." (PMID 37400936, 2023).